HTR1A (5-hydroxytryptamine receptor 1A)
Description:
G protein-coupled receptor for 5-hydroxytryptamine (serotonin). Also functions as a receptor for various drugs and psychoactive substances. Ligand binding causes a conformation change that triggers signaling via guanine nucleotide-binding proteins (G proteins) and modulates the activity of downstream effectors, such as adenylate cyclase. HTR1A is coupled to G(i)/G(o) G alpha proteins and mediates inhibitory neurotransmission: signaling inhibits adenylate cyclase activity and activates a phosphatidylinositol-calcium second messenger system that regulates the release of Ca(2+) ions from intracellular stores. Beta-arrestin family members regulate signaling by mediating both receptor desensitization and resensitization processes. Plays a role in the regulation of 5-hydroxytryptamine release and in the regulation of dopamine and 5-hydroxytryptamine metabolism. Plays a role in the regulation of dopamine and 5-hydroxytryptamine levels in the brain, and thereby affects neural activity, mood and behavior. Plays a role in the response to anxiogenic stimuli.
Synonyms: 5-HT-1A; 5-HT1A; ADRB2RL1; ADRBRL1; 5HT1a; G-21; PFMCD
Tractability: Small molecule: an approved drug acts on it; a structure with a bound ligand is known; a high-quality ligand is known; it belongs to a druggable protein family. Antibody: UniProt places it where antibodies can reach, with high confidence; its Gene Ontology location is reachable by antibodies, with high confidence; UniProt predicts a signal peptide or a membrane-spanning region. PROTAC: ubiquitination databases record sites on it; a small molecule that binds it is known. Other modalities: an approved drug acts on it.
Target class: Monoamine receptor; Family A G protein-coupled receptor; Small molecule receptor (family A GPCR); Serotonin receptor; Membrane receptor
Chemical probes: CHEMBL1774995, CHEMBL2164354, DPAT (high quality), PD081642
Safety:
Unwanted effects reported when the protein is acted on. In parentheses: how it was acted on, where the effect was seen, and who reports it.
cortisol secretion (Bowes et al. (2012): activation, central nervous system, endocrine; Lynch et al. (2017): activation, acute dosing, nervous system, endocrine, cardiovascular)
decreased body temperature (Lynch et al. (2017): activation, acute dosing, nervous system, endocrine, cardiovascular; Bowes et al. (2012): activation, central nervous system, endocrine)
growth hormone secretion (Bowes et al. (2012): activation, central nervous system, endocrine; Lynch et al. (2017): activation, acute dosing, nervous system, endocrine, cardiovascular)
increased adrenocorticotropic hormone (Lynch et al. (2017): activation, acute dosing, nervous system, endocrine, cardiovascular; Bowes et al. (2012): activation, central nervous system, endocrine)
decreased aggression (activation, acute dosing; nervous system, endocrine, cardiovascular; source: Lynch et al. (2017))
decreased anxiety (inhibition, acute dosing and activation, acute dosing; nervous system, endocrine, cardiovascular; source: Lynch et al. (2017))
decreased blood pressure (activation, acute dosing; nervous system, endocrine, cardiovascular; source: Lynch et al. (2017))
decreased memory (activation, acute dosing; nervous system, endocrine, cardiovascular; source: Lynch et al. (2017))
decreased pain (activation, acute dosing; nervous system, endocrine, cardiovascular; source: Lynch et al. (2017))
decreased sleep (inhibition, acute dosing; nervous system, endocrine, cardiovascular; source: Lynch et al. (2017))
decreased/increased locomotor activity (activation, acute dosing; nervous system, endocrine, cardiovascular; source: Lynch et al. (2017))
dizziness (inhibition, acute dosing; nervous system, endocrine, cardiovascular; source: Lynch et al. (2017))
increased heart rate (activation, acute dosing; nervous system, endocrine, cardiovascular; source: Lynch et al. (2017))
increased locomotor activity (inhibition, acute dosing; nervous system, endocrine, cardiovascular; source: Lynch et al. (2017))
increased memory (inhibition, acute dosing; nervous system, endocrine, cardiovascular; source: Lynch et al. (2017))
increased/decreased pupil diameter (activation, acute dosing; nervous system, endocrine, cardiovascular; source: Lynch et al. (2017))
increased/decreased sleep (activation, acute dosing; nervous system, endocrine, cardiovascular; source: Lynch et al. (2017))
paresthesia (inhibition, acute dosing; nervous system, endocrine, cardiovascular; source: Lynch et al. (2017))
potentially anxiogenic (inhibition; central nervous system, endocrine; source: Bowes et al. (2012))
reduced REM sleep (activation; central nervous system, endocrine; source: Bowes et al. (2012))
stereotypy (activation, acute dosing; nervous system, endocrine, cardiovascular; source: Lynch et al. (2017))
visual disturbances (inhibition, acute dosing; nervous system, endocrine, cardiovascular; source: Lynch et al. (2017))
methamphetamine psychosis (source: ClinPGx)
Gene: Protein-coding gene on chromosome 5 (63,957,874 to 63,962,507, reverse strand). Ensembl gene ENSG00000178394.
Subcellular location: Cell membrane; Cell projection, dendrite
Pathways (Reactome):
Signal Transduction: Serotonin receptors
Gene Ontology:
Molecular function: G protein-coupled serotonin receptor activity; Gi/o-coupled serotonin receptor activity; protein binding; receptor-receptor interaction; neurotransmitter receptor activity; serotonin binding; G protein-coupled receptor activity
Biological process: adenylate cyclase-inhibiting serotonin receptor signaling pathway; G protein-coupled receptor signaling pathway; behavioral fear response; chemical synaptic transmission; exploration behavior; G protein-coupled receptor signaling pathway, coupled to cyclic nucleotide second messenger; positive regulation of cell population proliferation; regulation of dopamine metabolic process; regulation of serotonin secretion; serotonin metabolic process; serotonin receptor signaling pathway; regulation of behavior; regulation of hormone secretion; regulation of vasoconstriction
Cellular component: plasma membrane; dendrite; membrane; synapse
Genetic constraint (gnomAD): Loss-of-function variants: 17 observed, 26.52 expected, observed/expected ratio (o/e) 0.64, 90% interval 0.44 to 0.96. The upper end of that interval is the gene's LOEUF score, 0.96, which puts it in group 4 of 6, group 1 being the genes least tolerant of losing a copy. Missense variants: 515 observed, 604.38 expected, observed/expected ratio (o/e) 0.85, 90% interval 0.79 to 0.92. Synonymous variants: 262 observed, 265.81 expected, observed/expected ratio (o/e) 0.99, 90% interval 0.89 to 1.09.
Homologues: Orthologues: chimpanzee HTR1A (99% identical), macaque HTR1A (98% identical), rabbit HTR1A (94% identical), guinea pig HTR1A (92% identical), pig HTR1A (91% identical), mouse Htr1a (88% identical), zebrafish htr1ab (67% identical), Caenorhabditis elegans ser-4 (36% identical). Paralogues in human: HTR1D (37% identical), DRD5 (29% identical), HTR4 (29% identical), DRD1 (28% identical), DRD4 (28% identical), DRD3 (28% identical), HRH2 (26% identical), HRH1 (26% identical), CHRM5 (26% identical), CHRM2 (26% identical), CHRM1 (25% identical), CHRM3 (25% identical), and 13 more.
Diseases named in the same sentence as HTR1A in open-access papers:
HTR1A is named in the same sentence as 186 diseases in open-access papers, as found by Europe PMC text mining. Sharing a sentence is not in itself a finding about the gene and the disease. The quoted sentences say what the papers report.
depression (287 papers, 2006 to 2026). "The rs6295 polymorphism in the HTR1A promoter affects 5-HT1A expression via the transcription factor Deaf-1, altering serotonergic activity and contributing to anxiety and depression mechanisms." (PMID 41373485, 2025). "Genetic studies have shown that HTR1A gene variation is associated with depression, especially a functional HTR1A SNP rs6295 in the promoter region was found to be associated with antidepressant pharmacogenetics in the different population." (PMID 39130405, 2024). "The 5-HT1A receptor is encoded by the HTR1A gene, and mutations in this gene have been linked to several neuropsychiatric disorders, including major depression, anxiety disorders, and autism spectrum disorder." (PMID 37239455, 2023). "Previous studies have suggested that HTR1A polymorphisms are associated with various mental diseases, such as major depressive disorder, obsessive-compulsive disorder, and anxiety disorder." (PMID 37161455, 2023). "Cefaclor consistently modulated mRNA expression of Htr1a, Htr1b, and Htr6 receptors, which are implicated in pathology of anxiety and depression, in the hippocampus." (PMID 37726354, 2023). "According to the viewpoint of biological susceptibility, some specific chromosomes, such as 15q and 12, and some genes, such as the serotonin receptor gene HTR1A, are associated with depression." (PMID 31906177, 2019). "Abnormal expression of the 5-HT1A receptor, which is encoded by the HTR1A gene, leads to susceptibilities to neuropsychiatric disorders such as depression, anxiety, and schizophrenia." (PMID 30766477, 2019). "In humans, altered regulation of the 5-HT1A gene (HTR1A) in depression was first suggested when we identified the association of the C/G(-1019) rs6295 HTR1A polymorphism, located in the 5-HT1A promoter region." (PMID 29636529, 2018). "HTR1A (5-Hydroxytryptamine Receptor 1A) is a protein associated with some diseases mainly depression, which is considered as a serious healthcare concern worldwide." (PMID 27454254, 2016). "Serotonin transporter (SLC6A4) and serotonin receptor (HTR1A, the 13rd) genes are among the strongest candidates underlying the etiology of depression." (PMID 21494644, 2011). "The serotonin 1A receptor (5HT1A) has been implicated in the regulation of neuroendocrine responses to stress in juvenile and adult animals, and the C(-1019)G polymorphism in the promoter region of the human htr1a gene is associated with depression and antidepressant treatment resistance." (PMID 39396089, 2025). "For instance, mutations in genes such as SLC6A4 and HTR1A may lead to abnormalities in the 5-HT system, increasing the risk of depression, anxiety, and other mental disorders." (PMID 39769209, 2024). "Indeed, deficits in the serotonin-1A receptor encoded by the HTR1A gene have been associated with depression and anxiety in heterozygous knockout mice and in their offspring." (PMID 36980856, 2023). "The 5-HT1A receptor gene (HTR1A) is situated on chromosome 5 (5q11.2-13), and recent studies have found that a common C1019G polymorphism located in its promoter region probably plays a role in depression and SB." (PMID 27721799, 2016). "However, in the human HTR1A promoter, Deaf1 fails to bind to its site at the rs6295 G-allele, leading to increased 5-HT1A autoreceptor expression to reduce serotonergic activity and predispose to depression." (PMID 27488351, 2016). "Moreover, a common genetic variant in the promoter of HTR1A in humans, that is thought to reduce its expression, is associated with suicide and depression." (PMID 25759645, 2015). "Although the connection between htr1a expression and chronic anxiety is not well understood, studies have shown that single nucleotide polymorphisms in the HTR1A gene, along with recent stressful life events, were associated with higher depression and anxiety scores." (PMID 38705984, 2024).
depression (continued). "In the field of depression, 5-HT-related genes (e.g., HTR1A, HTR2A, and SLC6A4) and their SNPs are also the predominantly researched pharmacodynamic genes." (PMID 37581520, 2024). "However, instead of developmental deficits and cognitive impairments, anxiety and depression-like behaviors were observed in Phf8 deficient mice, which is thought to be mediated by the direct regulation of serotonin receptors (5-Hydroxytryptamine receptor 1a/2a (Htr1a, Htr2a)." (PMID 39311138, 2024). "Polymorphisms in the 5-HT1A promoter (G/C (SNP) rs6295, HTR1A+272GG and others) have been associated with the development of major depressive disorder, suicide risk, and sensitivity to antidepressants." (PMID 38003611, 2023). "Altered HTR1A or other serotonergic genes’ methylation profiles have been documented in psychiatric diseases such as suicidal behavior, panic disorder, depression and anxiety disorder." (PMID 36980856, 2023). "Our study comprehensively focused on the antitumor potential of depression‐related genes and discovered HTR1A as a novel antitumor target in breast cancer." (PMID 35199941, 2022). "The serotonin receptor 1A (HTR1A) rs878567 and CYP2C19 rs12248560 gene variants are associated with depression severity." (PMID 33920985, 2021). "This study aims to estimate the contribution of 11 polymorphisms in the genes SLC6A4 (5HTT), HTR1A, HTR2A, HTR1B, SLC6A3 (DAT1), DRD4, DRD2, COMT, and BDNF to suicidal behavior and severity of symptoms of depression and anxiety in the Russian population." (PMID 34199792, 2021). "A recent review examining the 5-HT1A receptor in depression suggested interaction between BDNF and HTR1A as an important target for future PET studies." (PMID 30664620, 2019). "The substantial evidences supported the reduction in HTR1A or 5-HT1A receptor expression in patients with depression and schizophrenia." (PMID 31614865, 2019). "More research is needed to elucidate the roles of depression and antidepressant treatment on placental gene and protein expression, especially as regards HTR1A, and, further, the effect on the fetus." (PMID 31805950, 2019). "5-HT1A receptor is the dominant receptor of HTR1A and found to be responsible for depression and plays a role in the mechanism of action of several antidepressant drugs." (PMID 27454254, 2016). "Studies indicate that with inactivation of HTR1A in mice resulted in increased stress and anxiety.Flavonoids are considered as one of the promising safer alternatives to treat depression." (PMID 27454254, 2016). "Taken together these data suggest different and/or compensatory role of the two subpopulations of Htr1a heteroreceptor on both anxiety and depression-like behaviors." (PMID 25759645, 2015). "In human depression, changes in the Htr1a and Htr2a receptors have been reported and a 5-HT1A receptor polymorphism has been associated with depression." (PMID 20830301, 2010). "Depression may influence different gene polymorphisms, including COMT, ADRB2, and HTR1A genes, which are associated with chronic joint pain and TMD." (PMID 38836036, 2024). "Additionally, we evaluated the role of the SNP sites of HTR1A, HTR1B, S100A10, BDNF genes in depression patients through genetic association analysis." (PMID 39130405, 2024). "All in all, the enhanced gene expression of HTR1A in placentas from women with untreated depression, together with the stronger immunohistochemical staining of HTR1A in the treatment group, could strengthen the theory of the involvement of HTR1A in maternal depression and placental function." (PMID 31805950, 2019). "The serotonin receptors 5-HT1AR (also known as HTR1A) and 5-HT7R (also known as HTR7) have emerged as key players in stress-related disorders, particularly depression." (PMID 39279505, 2024).
depression (continued). "Among them, 5-HT1A (also known as HTR1A) and 5-HT7 (also known as HTR7) receptors have attracted considerable attention for their roles in mood disorders, such as depression and anxiety." (PMID 39279505, 2024). "Vilazodone, a 5 hydroxytryptamine receptor 1A (5-HT1A) partial agonist and selective reuptake inhibitor, has been approved by the FDA for the treatment of major depressive disorder in adults." (PMID 38702755, 2024). "In this study, we estimated the contribution of SLC6A4 (5HTT), HTR1A, HTR2A, HTR1B, SLC6A3 (DAT1), DRD4, DRD2, COMT, and BDNF genes to the suicidal behavior and severity of symptoms of depression and anxiety in the East-Slavic population of Russia." (PMID 34199792, 2021). "Nominally significant findings were noted for HTR1A and NPY2R, where women with untreated depression displayed higher gene expression than healthy controls (p < 0.05), whereas women on antidepressant treatment had similar expression as healthy controls." (PMID 31805950, 2019). "Post hoc analyses revealed that women with untreated depression had higher gene expression of HTR1A, (p = 0.039) and NPY2R (p = 0.025) than healthy controls, whereas women on antidepressant treatment had similar expression levels of HTR1A and NPY2R as healthy controls." (PMID 31805950, 2019). "Thus, we propose that epistasis between HTR1A and BDNF is a control element of the serotonergic system and may be involved in neuropsychiatric disorders as depression." (PMID 30664620, 2019).